ANXA2 (annexin A2)
Diseases named in the same sentence as ANXA2 in open-access papers (continued):
Sharing a sentence is not in itself a finding about the gene and the disease.
bladder urothelial carcinoma (6 papers, 2019 to 2024). "First, we must collect the tumor tissue samples from bladder urothelial carcinoma patients and relevant prognoses to confirm further the AnxA2 expression and its association with clinical outcomes." (PMID 36428758, 2022). "Among them, tripartite motif containing 65 (TRIM65) was reported to ubiquitylate ANXA2 in urothelial carcinoma of the bladder (UCB)." (PMID 38688909, 2024). "To investigate the role of AnxA2 in bladder urothelial carcinoma, we analyzed the expression of AnxA2 mRNA in normal bladder tissue samples (n = 19) and BLCA tissue samples (n = 409) from the TCGA database." (PMID 36428758, 2022). "A previous study reported that TRIM65 promoted bladder urothelial carcinoma progress via ubiquitination of ANXA2." (PMID 35977942, 2022). "Our study provides evidence that AnxA2 might be a potential therapeutic target and prognostic marker for Bladder Urothelial Carcinoma." (PMID 36428758, 2022). "In addition, our results also showed that high cell surface expression of AnxA2 in T24 cells produces a large amount of plasmin which plays an important role in angiogenesis and metastasis of high-grade bladder urothelial carcinoma." (PMID 36428758, 2022). "TRIM65 enhances the invasiveness of bladder urothelial carcinoma (BUC) cells by inducing epithelial–mesenchymal transition (EMT) and promoting the ubiquitination and degradation of Annexin A2 (ANXA2)." (PMID 31820796, 2019).
clear cell renal cell carcinoma (6 papers, 2009 to 2024). "In addition, Anxa2 is associated not only with clear-cell renal cell carcinoma differentiation but also the formation of calcium-related nephrolithiasis." (PMID 37955107, 2023). "DBT has been characterized as a tumor suppressor that inhibits tumor progression and corrects lipid metabolism disorders through the DBT/ANXA2/YAP axis-regulated Hippo signaling pathway in clear cell renal cell carcinoma." (PMID 38722401, 2024).
dysferlinopathy (6 papers, 2019 to 2024). "Microarray RNA analysis revealed an overexpression of annexin A2 in dysferlinopathy muscle compared with normal subjects." (PMID 39350328, 2024). "Together, these data show that expression of full-length dysferlin restores annexin A2 distribution in dysferlinopathy myoblasts." (PMID 31861684, 2019). "In addition, recent in vitro and in vivo studies demonstrated an active role of AnxA2 in the adipogenic conversion of muscle affected by dysferlinopathy." (PMID 36012197, 2022). "Therefore, we analyzed the distribution of annexin A2 and its colocalization with newly incorporated G-actin in control C25 and dysferlinopathy DYSF3 myoblasts." (PMID 31861684, 2019). "Moreover, we observe significant associations between the protein expression of ANXA1, ANXA2, ANXA4, ANXA5, LMNA, PYGM, and the extent of histopathologic changes in muscle biopsies from patients with dysferlinopathy, validated through immunoblotting and immunofluorescence assays." (PMID 39350328, 2024). "Noteworthy, the poor G-actin incorporation in dysferlinopathy myoblasts was restored by expression of both N- and C-terminal regions of dysferlin; however, the contribution of these dysferlin regions to annexin A2 distribution remains unclear." (PMID 31861684, 2019). "In aged dysferlin null mice and individuals with dysferlinopathy, lack of dysferlin alters expression of many dysferlin-associated proteins including AHNAK, Annexin A2, Calpain-3, Caveolin-3 and MG53." (PMID 36653852, 2023). "ANXA1 and ANXA2 interact with DYSF to mediate sarcolemma repair and both ANXA have been reported to be upregulated in Italian, American, or Australian patients suffering from dysferlinopathies." (PMID 34067866, 2021). "ANXA2 may act, therefore, as a modifying factor which strongly influences, in a negative way, clinical consequences of dysferlinopathies." (PMID 34067866, 2021). "Moreover, AnxA2-depleted mice showed extensive myofiber regeneration after laser injury, but not degeneration or adipogenic replacement, making AnxA2 a novel target to treat dysferlinopathy." (PMID 33810523, 2021).
HIV-1 infection (6 papers, 2009 to 2024). The type species of lentivirus and the etiologic agent of acquired immunodeficiency syndrome (AIDS). "AnxA2 is a crucial player in HIV-1 infection, directly interacting with HIV-1 proteins and impacting virus maturation; intriguingly, this process however is inhibited in the presence of SLPI." (PMID 39850816, 2024). "Mechanistically, SLPI has been shown to inhibit HIV-1 infection of macrophages by binding to and blocking cell surface annexin A2." (PMID 22927980, 2012). "ANXA2 antibodies impair productive HIV-1 infection of macrophages in vitro." (PMID 36786600, 2023). "As previously stated, annexin A2 was shown to be a cofactor for HIV-1 infection in macrophages, but until now, annexin A2 has never been associated with HPV16." (PMID 22927980, 2012). "Furthermore, an anti-A2 antibody impaired HIV-1 particle production in macrophages in vitro, whereas A2ti did not indicating that annexin A2 may promote HIV-1 infection of macrophages in its monomeric rather than tetrameric form." (PMID 27863502, 2016). "This suggests that Annexin A2 may promote the HIV-1 infection of the macrophage in monomeric form without the involvement of S100A10 dimer, which differs from the mechanism of HPV infection that involves the heterotetrameric molecule of Annexin A2." (PMID 37482693, 2023).
Infertility (6 papers, 2019 to 2025). "Notably, in humans, ANXA2 is typically detected only in sperm of excellent quality, whereas its under-expression has been associated with infertility." (PMID 41280419, 2025). "Validation of key proteins suggests that ANXA2 can be a screening biomarker for both primary and secondary infertility, whereas CDC42 and SEMG2 can be useful candidate biomarkers for primary infertility and APP for secondary infertility." (PMID 32372034, 2020). "Proteomic analysis revealed overexpression of ANXA2 in the seminal plasma of men with primary and secondary infertility." (PMID 32372034, 2020). "Western blot validation showed overexpression of ANXA2 and CDC42, and underexpression of SEMG2 proteins in primary infertility; and overexpression of ANXA2 and APP proteins in secondary infertility." (PMID 32372034, 2020). "Earlier studies have reported abnormal expression of ANXA2 in seminal plasma and prostasomes of subfertile or infertile men54–56." (PMID 32372034, 2020). "Another similar study compared seminal exosomal protein levels in fertile versus infertile men and distinguished that within the infertility group, many proteins were differentially expressed, including the upregulation of ANXA2 and the downregulation of KIF5B." (PMID 35980542, 2023). "In addition, the study of differentially expressed proteins related to varicocele mediated infertility showed that Nrf2 was an upstream regulator of ANXA2." (PMID 34744717, 2021). "Furthermore, WB findings also confirmed the overexpression of ANXA2 in both primary and secondary infertile men compared to control group." (PMID 32372034, 2020). "Our proteomic results in par with the Western blot results indicate that the overexpression of ANXA2 and underexpression of proteasomal proteins in the spermatozoa may lead to an impaired sperm function in normozoospermic infertile men." (PMID 31336797, 2019). "Other key proteins such as ANXA2 and APP were overexpressed in secondary infertility group compared with control group (p < 0.05)." (PMID 32372034, 2020). "Of the four validated proteins, SPA17 and SERPINA5 were underexpressed and ANXA2 was overexpressed (p < 0.05) in UMI subjects, whereas the expression level of PRDX2 was comparable for normozoospermic fertile and infertile men." (PMID 31336797, 2019).
metastatic tumors (6 papers, 2009 to 2023). "As AnxA2 is driven to the bone niche, it alters bone homeostasis, which is prevalent in bone-metastatic disease." (PMID 36839985, 2023). "Immunohistochemical analysis of patient ccRCC tissues revealed that annexin A2 was over-expressed in 47.4% of primary tumors and 87.5% of metastatic tumors." (PMID 23519104, 2013). "Ohno and colleagues investigated the expression of ANXA2 in clear cell RCC tissues and normal tissues, and detected upregulated expression of ANXA2 gene and protein in 14 of 18 primary RCC tissues, positive ANXA2 immunostaining in 73 of 154 primary RCC tissues, as well as 21 in 24 metastatic tumors." (PMID 36120574, 2022).
thyroid cancer (6 papers, 2010 to 2023). "Several members of this family have been linked to cancer, with annexin A2 being one of the most studied annexins and a known cancer biomarker, and annexin A4 also being associated with different cancers such as colorectal, gastric, and thyroid cancer." (PMID 37833989, 2023). "With regard to thyroid carcinoma, previous proteomic studies revealed increased levels of annexin A2, A5, A1." (PMID 24023790, 2013). "Furthermore, other L/R pairs identified in our analysis, namely INHBB/ACVR1 and TNC/ANXA2, have been shown to be involved in invasiveness of other solid tumors, and as they have not yet been studied in thyroid cancer, warrant further investigation in this context." (PMID 20877637, 2010).
brain tumor (5 papers, 2012 to 2024). "The annexin A2 protein encoded by ANXA2 is a key determinant of epithelia -mesenchymal transformation of brain tumor cells, and its functions outside the cell in anticoagulant reactions have been implicated." (PMID 32256671, 2020). "Of note, ANXA1, ANXA2, GNAS, HSP90AA1, HSP90AB1 and PSMD2, were highly abundant in EVs captured from GBM neurosurgical aspirates and in Pre-OP GBM uEVs here, implicating a potential brain tumour diagnostic utility for TRiC subunits and their interacting partners." (PMID 38212481, 2024). "Comparing our proteomic analysis with previous proteomic works on medulloblastoma and brain tumor exosomes, many proteins are shared, as expected: ACTB, G3P, GRP78, ANXA2, TRFE, CH60, HBB, HSP90." (PMID 26464805, 2015).
Cirrhosis (5 papers, 2013 to 2021). A chronic disorder of the liver in which liver tissue becomes scarred and is partially replaced by regenerative nodules and fibrotic tissue resulting in loss of liver function. "The sensitivity, specificity and diagnostic accuracy of tissue ANXA2 for HCC in cirrhosis were 78.2, 42.1 and 56.8%, respectively." (PMID 23946789, 2013). "Our results showed that ANXA2 expression was increased in patients with liver cirrhosis compared to those with non-cirrhosis." (PMID 34575275, 2021). "Notably, ANXA2 expression was positively correlated with cirrhosis, AST, anti-HCV antibody and the presence of capsule." (PMID 34575275, 2021). "Interestingly, both the tyrosine phosphorylation and protein expression of ANXA2 are elevated in HCC compared to normal or cirrhosis tissue." (PMID 24591759, 2014). "The primary objective of the present study was to clarify whether ANXA2 is a useful biomarker for distinguishing HCC from cirrhosis; the secondary objective was to evaluate the role of ANXA2 in predicting HCC recurrence following liver transplantation." (PMID 23946789, 2013). "Considering only the cirrhosis and non-cancer tissues as non-malignant, the sensitivity, specificity and diagnostic accuracy of ANXA2 were 78.2, 42.1 and 56.8%, respectively." (PMID 23946789, 2013). "However, the serum ANXA2 levels were also clearly elevated in the patients with cirrhosis compared with the healthy controls." (PMID 23946789, 2013). "ANXA2 expression is not a good serological or immunological diagnostic marker for differentiating HCC from cirrhosis." (PMID 23946789, 2013). "Compared with the non-cirrhosis group, the liver cirrhosis group had higher anti-HCV-positive rate, smaller tumor size, higher proportion of high ANXA2 expression, longer PT prolongation and lower AST level." (PMID 34575275, 2021). "ANXA2 is significantly increased in the sera of HCC compared with the sera from healthy, benign tumor, hepatitis, and cirrhosis controls and other malignant tumors." (PMID 24591759, 2014). "The serum levels of ANXA2 were significantly elevated in the patients with HCC (median, 567.2 μg/ml; P=0.003) and cirrhosis (median, 414.8 μg/ml; P=0.011) compared with the healthy controls (median, 241.9 μg/ml)." (PMID 23946789, 2013). "In the present study, a typical multistage hepatocarcinogenesis model (healthy, cirrhosis and HCC) was used to evaluate the roles of serum and tissue ANXA2 in the diagnosis of HCC." (PMID 23946789, 2013). "The serum levels of ANXA2 were significantly increased in the patients with HCC (median, 567.2 vs. 241.9 μg/ml; P=0.003) and cirrhosis (median, 414.8 μg/ml vs. 241.9 μg/ml, P=0.011) compared with the healthy controls." (PMID 23946789, 2013). "A marked correlation was observed between the serum and tissue ANXA2 levels in the patients with HCC and cirrhosis." (PMID 23946789, 2013). "Considering the healthy controls and the cirrhosis and non-cancer tissues as non-malignant, the sensitivity, specificity and accuracy of ANXA2 for HCC detection were 78.2, 52.3 and 61.7%, respectively." (PMID 23946789, 2013). "Furthermore, the cancer tissues (16/87, 18.4%) showed a higher marked ANXA2 staining rate (+++) compared with the non-cancer (4/87, 4.6%, P=0.004) and cirrhosis (1/39, 2.6%, P=0.016) tissues." (PMID 23946789, 2013). "Therefore, neither serum nor tissue ANXA2 would be a good biomarker for HCC patients with a history of cirrhosis." (PMID 23946789, 2013).
ischemic stroke (5 papers, 2021 to 2025). A stroke disorder caused by obstruction of blood flow to the brain, due to thrombotic (local blood clot formation) or embolic (due to a blood clot or other material traveling from another site) event. "Administering a combination of low‐dose tissue‐type plasminogen activator (tPA) plus recombinant human Annexin A2 (rA2) four hours post‐ischemic stroke yields superior enhancement in neurological function recovery." (PMID 39912333, 2025). "We detected the specific expression of C1QA and Casp14 in the EVs of patients with CSC ischaemic stroke and the specific expression of ANXA2 in the EVs of patients with SC involvement." (PMID 34356850, 2021). "Ischemic stroke did not cause a substantial change in the relative expression of AnxA2, AnxA5, AnxA6, and AnxA7 in the cortical neurons in reference to sham controls." (PMID 39820937, 2025). "Ischemic stroke notably resulted in a substantial reduction in Anxa2 expression." (PMID 39912333, 2025). "Anxa2 promotes angiogenesis after ischemic stroke via AKT/ERK pathways." (PMID 38253182, 2024). "In ischemic stroke induced at 3 days after Anx siRNA administration, the levels of brain CaP deposition and infarction were significantly reduced in response to Anx gene silencing (except for AnxA2 siRNA) in reference to the levels with control siRNA administration." (PMID 39820937, 2025). "Thus, our study suggested that targeting the Anxa2-related inflammatory pathway or inflammation-related neuronal damage might offer unique insights into ischemic stroke's pathological processes and help establish effective therapeutic strategies." (PMID 38253182, 2024). "Moreover, mitochondrial translocation of p‐Anxa2 and p‐Akt (p < 0.05), and the interactions between p‐Anxa2 and p‐Akt in the mitochondria (p < 0.05) were elevated in diabetic rats subjected to ischemic stroke following lncRNA‐MEG3 silencing, as detected by WB and COIP assays, respectively." (PMID 39912333, 2025).
laryngeal carcinoma (5 papers, 2014 to 2023). Carcinoma that arises from the laryngeal epithelium. "have uncovered that ANXA2 is highly expressed in laryngeal carcinoma and its expression is associated with tumor size, distant metastasis and clinical stage." (PMID 36998449, 2023). "For instance, the AnxA2 expression is significantly associated with tumor size, lymph node metastasis, distant metastasis and clinical stage of laryngeal cancer, and therefore it is a promising candidate for estimating the prognosis of patients with laryngeal carcinoma or gliomas." (PMID 29914106, 2018).
metastatic carcinoma (5 papers, 2020 to 2023). A carcinoma which has spread from the original site of growth to another anatomic site. "S100A11 has also been shown to associate with ANXA2 and this interaction is required for efficient PM wound repair and subsequent survival of metastatic cancer cells." (PMID 36200035, 2022). "The recent authoritative review by Sharma discusses these studies and similar findings in a number of cancer types and concluded by proposing Annexin A2 to be a universal signature of aggressive and metastatic cancer." (PMID 32629869, 2020). "Annexin A2 has been proposed as a potential biomarker and therapeutic target for aggressive and metastatic cancers." (PMID 32629869, 2020). "Similar to ANXA1, ANXA2 may elicit either tumor-promoting or -suppressive mechanisms depending on the cancer type; however, ANXA2 is frequently enhanced in metastatic cancers." (PMID 36247003, 2022). "Our results suggest that Annexin A2's role in promoting cancer progression is mediated by collagen-I and Annexin A2 maybe a therapeutic target in the bi-directional cross-talk between cancer cells and ECM remodeling that supports metastatic cancer progression." (PMID 37941562, 2023).
serous ovarian cancer (5 papers, 2013 to 2025). "The increased ANXA2 mRNA in stage III serous ovarian cancer is associated with the reduced survival." (PMID 41497316, 2025). "In serous ovarian cancer cells, annexin A2 immunostaining was present predominantly in the membrane and cytoplasm but high annexin A2 immunostaining was also noted in the cancer associated stroma." (PMID 23945256, 2013). "Strong annexin A2 immunostaining was observed in 90% (38/42) of the serous ovarian cancer cells and was significantly increased in the cancer-associated stroma compared to non-malignant ovarian tissues." (PMID 23945256, 2013). "Real-time PCR results showed annexin A2 was expressed in human serous ovarian cancer cell lines (OVCAR-3, OVCAR-5, SKOV-3 and OV-90) and the peritoneal cell line, LP-9." (PMID 23945256, 2013). "Annexin A2 siRNA significantly inhibited the motility and invasion of serous ovarian cancer cells and adhesion to the peritoneal cells." (PMID 23945256, 2013). "Stromal annexin A2 immunostaining in the invasive serous ovarian carcinomas (stage I to IV) was significantly increased compared with normal ovaries, serous cystadenomas, or serous borderline tumors (P < 0.0001)." (PMID 23945256, 2013). "The aim of this study was to investigate an inhibitor of the annexin A2 signalling pathway, all-trans retinoid acid (ATRA), for its efficacy to inhibit serous ovarian cancer cell survival and invasion." (PMID 30621740, 2019). "This study evaluated the effects of ATRA on annexin A2 and S100A10 expression, plasmin activation, and the ability of ATRA to inhibit serous ovarian cancer cell survival and invasion." (PMID 30621740, 2019). "In this study we determined the effects of ATRA treatment (1-5 μM) on annexin A2 and S100A10 expression, plasmin activation, and the ability of ATRA to inhibit serous ovarian cancer cell survival, motility and invasion in vitro." (PMID 30621740, 2019).